PIN1 (peptidylprolyl cis/trans isomerase, NIMA-interacting 1)
Diseases named in the same sentence as PIN1 in open-access papers (continued):
Sharing a sentence is not in itself a finding about the gene and the disease.
tumor (continued). "Research involving animals indicates that the absence of Pin1 hinders the development of oncogenes and inhibits both tumor and cellular proliferation." (PMID 38544686, 2024). "This combination creates a positive feedback loop of PIN1 inhibition and APC/CCDH1 activation, which may lead to synergistic anti-tumor efficacy." (PMID 38622115, 2024). "As expected, compared to non-tumor cells, PIN1 protein levels were notably higher in tumor cells and even further increased after disease progression and positively correlated with the proliferation marker Ki67." (PMID 38622115, 2024). "Therefore, simultaneous inhibition of Pin1 and CDK1 elevated apoptosis, decreased proliferation, and impacted stemness of tumor cells to delay tumor growth." (PMID 38167292, 2024). "Furthermore, by blocking Pin1, therapy based on a combination of ATO and all-trans retinoic acid (ATRA) has been proven effective against tumor-initiating cells, particularly in triple-negative breast cancer." (PMID 39624096, 2024). "Since As2O3 treatment had beneficial tumor and TIME effectsbut significant toxicity, we next analyzed whether modified ANs couldprovide similar Pin1 inhibition and antitumor effects as As2O3 but with reduced toxicity." (PMID 39051165, 2024). "Pin1 inhibition in PDAC decreased collagen deposition and “cleared” the desmoplastic TME, thereby promoting molecular exchange, increased CD8+ T-cell infiltration, and increased PD-L1 expression on tumor cells." (PMID 38745861, 2024). "Furthermore, Pin1 interacts with the CDK1/2 kinase and Cul3-KLHL20 Ub ligase to degrade promyelocytic leukemia (PML), which is a tumor suppressor that typically prevents HIF-1α translation by suppressing mTOR after HIF-1α activation." (PMID 38727267, 2024). "Taken together, our findings reveal the previous unrecognized tumor-promoting function of CDK1/PIN1 axis through destabilizing pVHL and provide the preclinical evidence that targeting CDK1/PIN1 is an appealing strategy in the treatment of multiple cancers with wild-type VHL." (PMID 36813923, 2023). "Gene expression analysis of tumor and non-tumor samples from the TCGA cohort showed that Pin1 mRNA expression was higher in TGCT samples than in non-tumor (normal testis) samples." (PMID 38020885, 2023). "The results showed a reduced tumor burden in Juglone‐treated tumor and immunohistochemistry showed a reduction in PCNA expression of Juglone‐treated tumor, indicating that Pin1 inhibition inhibits tumor proliferation in vivo." (PMID 36684109, 2023). "Pin1 inhibitor combined with PD-1 antibody and gemcitabine (GEM) synergistically destroys tumor fibrosis, improves the inhibition of TME, and achieves the level of tumor elimination." (PMID 36759842, 2023). "As a result of these findings, the tumour suppressor, DAPK-1, might eventually lead to more effective cancer therapeutic strategies by suppressing Pin1 oncogenic activity." (PMID 37372454, 2023). "Indeed, Pin1 was highly expressed in xenograft-forming PCNSL tumors, which enhanced tumor progression partially via NF-κB activation." (PMID 38089883, 2023). "PCR products derived from Pin1 mRNA were observed in tumor-initiating Caco-2 cells and in non-tumor-initiating Caco-2 cells." (PMID 35433695, 2022). "Taken together, these results suggest that Pin1 activity is essential for CD44+CD133+ tumor-initiating Caco-2 cell-induced tumorigenesis in vivo, and that Juglone or KPT6566 effectively inhibit tumor-initiating Caco-2 cell-mediated tumor growth." (PMID 35433695, 2022). "The prolyl isomerase Pin1, whose overexpression in CAFs has not been fully profiled yet, plays critical roles in tumor initiation and progression." (PMID 35879297, 2022). "For example, the inhibition of PIN1 with PiB reduced the rate of MYC binding to target DNA promoters in MCF10A cells, leading to decreased expression of oncogenic gene signatures and decreased tumor growth." (PMID 32300594, 2020).
tumor (continued). "In Ras-activated tumor cells, the function of FAK and PTP-PEST are also regulated by Pin1." (PMID 32296699, 2020). "Both in vitro and in vivo experiments have demonstrated that PIN1 over-expression in non-tumorigenic liver cells induces the colony formation in soft agar and tumor formation in nude mice." (PMID 32010690, 2019). "Thus, ATO binding to Pin1 is essential for ATO to induce Pin1 degradation, block oncogenic pathways, and inhibit tumor growth." (PMID 30093655, 2018). "Given the effects of ATRA on cell growth, leukemogenesis, Pin1 protein levels, and the downstream in AML in vitro, a critical question is whether ATRA suppresses AML tumor growth in vivo." (PMID 29848341, 2018). "Thus, ATO and ATRA cooperatively ablate Pin1 to inhibit the self-renewal, drug resistance, tumor initiation, and growth of TICs in TNBC, similar to Pin1 KO." (PMID 30093655, 2018). "Pin1 knockdown potently inhibited HCC cell proliferation and tumor growth in mice." (PMID 28262728, 2017). "Silencing Pin1 expression in multiple human HCC cell lines by a validated shRNA not only potently inhibited HCC cell proliferation and migration, but also suppressed HCC tumor growth in mice." (PMID 28262728, 2017). "Altogether these data strongly indicate that targeting PIN1 dismantles oncogenic pathway cooperation in CSCs and non-CSC tumour cells, providing a rationale for the development of PIN1 targeted therapies." (PMID 28598431, 2017). "To examine whether Pin1 affects HCC tumorigenesis in vivo, we performed xenograft tumor growth assay in nude mice." (PMID 28262728, 2017). "Given the critic role of Pin1 in HCC development, we investigate whether Pin1 plays a role in anti-tumor effects of sorafenib in HCC." (PMID 28404959, 2017). "We have packaged ATRA in slow-releasing microparticles, which alone shows more potent inhibitory activity both on Pin1 degradation in vitro and HCC tumor growth in vivo (data unpublished), indicating that developing novel slow-releasing method applicable to patients is worth further exploring." (PMID 28262728, 2017). "Given the potent ability of the Pin1 chemical inhibitor ATRA to enhance sorafenib-induced cell death in HCC cell lines, a critical question is whether ATRA would affect the anti-tumor efficacy of sorafenib in HCC in vivo." (PMID 28404959, 2017). "Together, our findings demonstrate that Pin1–Notch3 axis may reinforce Notch signaling effect in T-ALL, by influencing tumor grade and aggressiveness, finally suggesting that their combined inhibition may be exploited in target therapy protocols." (PMID 26876201, 2016). "Importantly, simultaneous knockdown of Pin1 and overexpression of ATF1 in CNE1 cells (CNE1:ATF1/shPin1) led to tumor formation much slower than overexpression of ATF1 in CNE1 cells (CNE1:ATF1)." (PMID 28032861, 2016). "The particular Pin1-dysregulated substrates and pathways are not mutually exclusive, and many of them are affected in cell type- and tumor type-specific combinations." (PMID 25588053, 2015). "Co-immunoprecipitation and gene knockout studies have shown that Pin1 interacts with multiple AUBPs (AUF1, HuR, and KSRP,) and RNA-binding protein (SLBP) in tumor and immune cells although the interaction may depend on cell type and environmental stimuli." (PMID 25874604, 2015). "Under normal conditions in noncancerous tumors, evidence suggests that Pin1 acts in a general tumor suppressive capacity." (PMID 25588053, 2015). "In addition, PIN1 and DDB1 proteins, also known to regulate HBx protein stability, were significantly overexpressed in tumor tissues in 35 (87.5%) samples and in 19 (42.2%) samples, respectively." (PMID 25361011, 2014).
tumor (continued). "The immunoreactive score for PIN1 was significantly higher in the tumor cells (4.07±0.4) compared with that of the adjacent non-neoplastic bile duct cells (1.19±0.4; P<0.001)." (PMID 24179535, 2013). "The results of the present study indicated a possible role for PIN1 in ECC development and also indicated that PIN1 expression may be involved in the proliferation and invasion of tumor cells." (PMID 24179535, 2013). "The combination of PIN1 inhibitor and CDK4 inhibitor thus enhances anti-tumor immunity, with decreased Tregs, increased cytotoxic T cells and evidence for tumor cell phagocytosis, raising the possibility that this rewiring of the immune system could further improve the therapeutic effect." (PMID 38622115, 2024). "Therefore, we propose that PIN1 may function as a key mediator of PML-NB during OIS and is necessary for the upregulation of tumor suppressor genes in response to RasG12V activation." (PMID 38216124, 2024). "How much Pin1 in CAFs contributes to tumor progression, however, is unknown since the lack of drugs exclusively blocking Pin1 in CAFs." (PMID 35879297, 2022). "Pin1 isomerizes both Ser910-phosphorylated FAK and Ser571-phosphorylated PTP-PEST to enhance the interaction between PTP-PEST and FAK, leading to the dephosphorylation of FAK Tyr397 by PTP-PEST and the promotion of migration, invasion, and metastasis of Ras-related tumor cells." (PMID 32296699, 2020). "However, no study has concentrated on Pin1‐NF‐κB‐mediated tumour progression and metastasis in PDAC." (PMID 32347623, 2020). "Pin1 also catalyzes the isomerization of Pro205 of Brd4 and induces its conformational change through a cis-trans isomerization, which leads to enhanced CDK9 binding to Brd4 and enhanced recruitment of CDK9 to a subset of promoters of Brd4-mediated tumor-promoting genes, including c-MET and MMP9." (PMID 32266261, 2020). "Moreover, the Pin1 chemical inhibitor ATRA not only enhanced the ability of sorafenib to induce cell death of multiple human HCC cells in vitro, but also synergistically potentiated sorafenib to suppress human HCC tumor growth in mice." (PMID 28404959, 2017). "Since the original hypothesis of this study is that Pin1 is a downstream target of miR-140-5p, we would expect that Pin1 knockdown might not further enhance the tumour suppressive functions of miR-140-5p in Huh7 cells as detected by transwell migration assay." (PMID 28383568, 2017). "Pin1 protein expression of 56 ESCC tumor and corresponding non-tumor tissues was determined." (PMID 25160749, 2014). "We further determined Pin1 mRNA level of 42 tumor and corresponding non-tumor specimens." (PMID 25160749, 2014). "Furthermore, it remains to be addressed whether the CDK1/2-Pin1 and the ERK2/Pin1 mechanisms to ubiquitinate PML are complementary, mutually exclusive, or tumor type specific." (PMID 23526763, 2013). "However, PIN1 expression was not significantly correlated with other clinicopathological parameters, including tumor differentiation, lymph node metastasis, distant metastasis, nerve invasion, gross type and tumor stage." (PMID 24179535, 2013). "However, here FK506 treatment only elevated Pin1 activity by ~ 35%, and treated mice showed no untoward effects including metabolic derangements, behavioral abnormalities, gross tissue pathology, or tumor development during FK506 treatment." (PMID 37849016, 2023). "In addition to tumor cells, Pin1 also promotes the proliferation of nontumorous cells." (PMID 33807199, 2021). "Moreover, Pin1 is highly enriched in breast TICs and drives TIC self-renewal and tumor initiation and growth, but whether Pin1 inhibitors would effectively target TICs is not known." (PMID 30093655, 2018).
tumor (continued). "It had been reported that Pin1 was not an oncogene itself, but it can serve as a translator and amplifier; play a crucial role in the process of transforming an oncogene to the signal of cell proliferation, differentiation, and apoptosis; and is upregulated in various types of tumor tissues." (PMID 27029791, 2016). "Since DAPK is a tumor suppressor, in tumor cells that have a reduction in DAPK, DAPK is not present to tightly regulate Pin1′s activity, leading to hyperactive Pin1." (PMID 31861908, 2019). "In primary human breast tumors, the expression of Pin1 is 5 and 30 times higher in non-CSC tumor cells and CSCs, respectively, compared with normal breast epithelial cells." (PMID 29848341, 2018). "The prolyl isomerase PIN1 represents a critical player in several signalling circuitries characterizing both CSCs and non-CSC tumour cells." (PMID 28598431, 2017). "By comparing HCC tumor tissues and paired adjacent non-cancerous liver tissues (ANLTs) of 25 HCC patients, we found that Pin1 was overexpressed in about 64% (16/25; T 1-5) of HCC tissues, which was consistent with the previous findings." (PMID 28383568, 2017). "Since the endogenous PIN1 and PIN4 levels remained higher in HBV replicating and non-replicating HCC-derived cell lines, we examined PIN1 and PIN4 levels in the biopsied tumor and non-tumor adjacent liver tissues obtained from eight patients of HBV-associated HCC." (PMID 36760500, 2023). "Notably, high expression of PIN1 (62/71, 87.32%) and CDK1 (60/71, 84.51%) were detected in most tumor specimens, while weak or none staining signals of pVHL was detected (55/71, 77.46%)." (PMID 36813923, 2023).
neurodegenerative disease (21 papers, 2016 to 2025). A disorder of the central nervous system characterized by gradual and progressive loss of neural tissue and neurologic function. "In this section, we will examine recent advancements in our understanding of Pin1’s role in negatively regulating the stability and ubiquitin-mediated degradation of proteins associated with neurodegenerative diseases, specifically AD, PD, and HD." (PMID 38727267, 2024). "For example, Pin1 orthologs from D. rerio (DrPin1), C. elegans (Pinn-1) and D. melanogasta (Dodo) have been linked to neurodegenerative diseases." (PMID 36111342, 2022). "Taken together, studies about Pin1, particularly those done in mice models, show that Pin1’s role in the pathology of neurodegenerative diseases makes Pin1 an attractive drug target in alleviating such disorders." (PMID 36111342, 2022). "Accordingly, a growing body of evidence suggests that Pin1 plays a crucial role in the pathophysiology of several neurodegenerative diseases." (PMID 33083964, 2021). "Although emerging evidence has shown that Pin1 directly or indirectly regulates neuronal proteins such as Tau, amyloid precursor protein (APP), and α-synuclein, the physiological functions of Pin1 in neurodegenerative diseases remain to be elucidated." (PMID 33537091, 2021). "Although Pin1 is tightly regulated under physiological conditions, Pin1 deregulation in the brain contributes to the development of neurodegenerative diseases, including AD." (PMID 32500074, 2020). "Pin1 has been previously found to modulate protein aggregate formation in other neurodegenerative diseases." (PMID 27199664, 2016). "Therefore, a differential role of Pin1 within the different neurodegenerative diseases clearly emerges and it is still subject of scientific debate." (PMID 33083964, 2021). "Moreover, we will discuss evidence from the literature supporting the notion of a differential role of Pin1 within the different neurodegenerative diseases." (PMID 33083964, 2021). "Furthermore, the Pin1 deficit contributes to many degenerative diseases, including AD28, HD29, and PD27, all of which are related to aberrant neuronal senescence and apoptosis." (PMID 30158600, 2018). "Despite impressive research and therapeutic advances in both fields of preE and neurodegenerative diseases, further investigation of Pin1-cis P-tau and ApoE-related mechanistic underpinnings may unravel novel therapeutic options, and new transcriptional and proteomic markers." (PMID 39857613, 2024).
infection (17 papers, 2009 to 2025). The state of being infected such as from the introduction of a foreign agent such as serum, vaccine, antigenic substance or organism. "Moreover, Pseudomonas syringae has been shown to increase plant susceptibility to infection by disrupting auxin synthesis or transport mediated by PIN1 in Arabidopsis thaliana." (PMID 40332284, 2025). "Subsequently, stable PIN1-silenced SiHa and ME-180 cells were established by infection with lentivirus and selected using puromycin." (PMID 35983979, 2022). "PIN1 and NF- κB mRNA levels were significantly downregulated after the infection, MHC-I, IRF3, and MAPK7 expressions were significantly upregulated following infection, whereas RMBX expression showed almost no variation." (PMID 29062054, 2017). "The infection efficacy was confirmed by a decrease in the protein and mRNA expression levels of Pin1." (PMID 29050342, 2017). "Our infection experiments on the mutant lines showed that, compared to the wild-type line En-2, the pin1 mutant contained significantly fewer nematodes inside the roots at both 3 and 7 DAI." (PMID 27312670, 2016). "These experiments confirmed that interactions of JNK, integrase and Pin1 are likely similar following infection of resting and activated CD4+ T cells and are critical for HIV infection." (PMID 27459960, 2016). "In support of this, infection studies using mutants defective in PIN1 and PIN2 have revealed a significant reduction in development of the cyst nematode Heterodera schachtii." (PMID 19148279, 2009). "The effect of Pin1 inhibition on herpesviral replication efficiency was analysed using an established HCMV green fluorescent protein (GFP)-based reporter assay at day 7 post-infection." (PMID 27556400, 2016). "Infection studies revealed that particularly PIN1 is at play during this process." (PMID 19148279, 2009). "During the HBV course of infection, Juglone, PiB, ATRA, 6,7,4′-THIF, KPT6566, and EGCG-mediated inhibition of PIN1 and PIN4 significantly lowered HBV transcriptional activities without affecting total levels of covalently closed circular DNA (cccDNA)." (PMID 36760500, 2023). "PLC/PRF/5 (HBV-positive), Huh-7 (HBV-negative) and several other HCC cells (including Hep3B and Sk-Hep-1, data not shown) became unhealthy after infection with lentiviruses expressing Pin1 shRNA, as compared with scrambled shRNA." (PMID 28262728, 2017). "An increase in Pin1 levels was also observed for infection with HSV-1, VZV, or RhCMV (lanes 4–14), but not as efficient as seen for HCMV." (PMID 27556400, 2016). "The expression pattern of the gene encoding the PIN1 auxin efflux carrier, a protein which is responsible for acropetal auxin transport through the root stele towards the root tip, did not seem to change strongly upon RKN infection in Arabidopsis." (PMID 27312670, 2016). "Upon infection with Listeria monocytogenes, Pin1-null mice were defective in stimulating proliferation of adoptively transferred WT CD8+ T cells, suggesting that decreases in Pin1 null CD8+ cDC may affect T cell responses to infection in vivo." (PMID 22238658, 2012). "Consistent with reduced numbers of CD8+ cDC in Pin1-null mice, we find that the absence of Pin1 impairs CD8+ T cell proliferation in response to infection with Listeria monocytogenes." (PMID 22238658, 2012).